CHGA (chromogranin A)
Diseases named in the same sentence as CHGA in open-access papers (continued):
Sharing a sentence is not in itself a finding about the gene and the disease.
breast carcinoma (12 papers, 2011 to 2025). "It is defined as uncommon subtype of breast cancer in which more than 50% of the tumor cells express at least one neuroendocrine marker (synaptophysin, chromogranin A, or neuron-specific enolase)." (PMID 33692758, 2021). "As an additional result, we demonstrated that VGF a recently described NE marker showing similarities with members of the secretogranin/chromogranin family is also expressed in NE breast cancers producing CHGA and/or SYP." (PMID 24277232, 2014). "As detailed in the Introduction, immunostaining with ENO2, chromogranin A and synaptophysin have been used extensively to determine neuroendocrine differentiation in breast cancer." (PMID 22098917, 2011). "Indeed, when in some studies neuroendocrine markers have been screened from unselected breast carcinomas, up to 10.4% of all breast cancers showed some synaptophysin or chromogranin A expression." (PMID 28118820, 2017). "Currently, NE differentiation in breast cancers has been assessed by immunohistochemical procedures detecting “general” NE markers such as chromogranin A (CHGA) and synaptophysin (SYP), and elucidation of specific hormonal peptides has been absent or unproductive." (PMID 24277232, 2014). "With the advent of the IHC techniques, with chromogranin A (CGA) and SYN as the most sensitive and specific markers, it is possible to identify the neuroendocrine phenotypes in this breast cancer subpopulation." (PMID 40297647, 2025). "Over-expression of one or more NE marker (CHGA and/or SYP and/or VGF) characterizes a significant fraction (approximately 10 %) of infiltrative breast cancers." (PMID 24277232, 2014). "In our case, chromogranin A, synaptophysin, CD56, and TTF1 were not stained initially, and the diagnosis was triple negative primary bilateral breast cancer." (PMID 39292386, 2024).
gastric cancer (12 papers, 2012 to 2024). A primary or metastatic malignant neoplasm involving the stomach. "The differences in positive rates of chromogranin A (CgA) and Ki-67 were analyzed by univariate Cox regression analysis as independent risk factors that may affect the survival of gastric cancer patients." (PMID 36035314, 2022). "We found expression of the neuroendocrine marker chromogranin A in gastric carcinomas in patients with pernicious anaemia and initially classified as adenocarcinomas." (PMID 34948181, 2021). "Chromogranin A was also shown in gastric carcinoma cells by in situ hybridization." (PMID 37941554, 2023). "Therefore, we examined the two gastric cancer cells for ECL markers chromogranin A (CgA) and synaptophysin (Syn) by immunocytochemistry and immunofluorescence, and negative staining was observed for CgA and Syn in both SGC-7901 and AGS cells." (PMID 34976177, 2022). "CHGA expression correlates with better prognosis in SRC-gastric carcinoma." (PMID 29484116, 2018). "We identified REG1A, CHGA, TFF2, ATP4A and ATP4B to be downregulated in intestinal gastric cancer, and Rajkumar and co-workers found ATP4A and ATP4B to be downregulated in gastric tumor tissues compared to normal tissues." (PMID 29484116, 2018). "Moreover, no chromogranin A positive cells were shown to divide in gastric carcinomas, and therefore chromogranin A positive tumour cells were claimed to be quiescent cells without any role in tumorigenesis." (PMID 34948181, 2021).
Anxiety (11 papers, 2010 to 2025). Intense feelings of nervousness, tension, or panic often arise in response to interpersonal stresses. "The following are promising salivary biomarkers of stress, anxiety or depression: cortisol, immunoglobulin A (sIgA), lysozyme, melatonin, α-amylase (sAA), chromogranin A (CgA) and fibroblast growth factor 2 (FGF-2)." (PMID 33535653, 2021). "A recent study concluded that anxiety positively correlated with plasma ChgA and catestatin levels." (PMID 36826581, 2023). "Results obtained from these salivary biomarkers offer insight into individuals’ stress levels, anxiety or depression, primarily using salivary cortisol, immunoglobulin A (sIgA), salivary alpha-amylase, chromogranin A, lysozyme, melatonin, and fibroblast growth factor 2 (FGF-2)." (PMID 36285968, 2022). "In the literature, you can find publications indicating the relationship between stress, depression and/or anxiety and the concentration of cortisol, immunoglobulin A, lysozyme, melatonin, alpha-amylase, chromogranin A and/or fibroblast growth factor 2 in saliva." (PMID 33535653, 2021). "We postulated that the chromogranin A reduction group experienced tension and anxiety before NPPV." (PMID 32257373, 2020). "However, there are no reports on the level of salivary chromogranin A in people diagnosed with depression or anxiety." (PMID 33535653, 2021).
irritable bowel syndrome (10 papers, 2008 to 2025). Irritable bowel syndrome (IBS) is a chronic functional condition of the lower gastrointestinal (GI) tract characterized by abdominal pain or discomfort and disordered bowel habit (diarrhea, constipation, or fluctuation between the two). "Among others, Chromogranin A has been negatively correlated with gut microbial diversity and has been shown to be increased in irritable bowel syndrome (IBS) patients as well as to correlate with abdominal pain in IBS." (PMID 38783385, 2024). "Chromogranin A (CgA) is a common marker for the gastrointestinal endocrine cells, and it is abnormal in irritable bowel syndrome (IBS) patients." (PMID 25918524, 2015). "In a previous study, chromogranin A (CgA) cell density in the colon of patients with irritable bowel syndrome (IBS) was found to be reduced." (PMID 22992886, 2012). "Psychophysiological processing has been reported to play a crucial role in irritable bowel syndrome (IBS) but there has been no report on modulation of the stress marker chromogranin A (CgA) resulting from muscle stretching." (PMID 18983682, 2008).
medullary thyroid carcinoma (10 papers, 2001 to 2022). "Medullary thyroid carcinoma is positive for chromogranin A, and this differential diagnosis can be especially difficult due to manifold histological structure of medullary thyroid carcinoma." (PMID 35805976, 2022). "Medullary thyroid carcinoma (MTC) is a rare thyroid carcinoma of C-cell deviation that produces and secretes calcitonin (CT) and chromogranin A (CgA) into the blood." (PMID 33485291, 2021). "We conclude that chromogranin A measurement is not recommended for the diagnosis of medullary thyroid carcinoma patients." (PMID 11259096, 2001). "Medullary thyroid carcinoma is able to produce other relevant biomarkers as procalcitonin, carcinoembryionic antigen and chromogranin A. In Literature are described few cases of medullary thyroid carcinoma without elevation of serum calcitonin, an extremely rare event." (PMID 31142313, 2019). "The tumors were consistent with a neuroendocrine phenotype; showing strong immunoreactivity to chromogranin A and synaptophysin, but the immunohistochemical profile was inconsistent with medullary thyroid carcinoma in that the tumor was negative for calcitonin, CEA and TTF-1." (PMID 22369355, 2012). "Neoplastic cells showed strong immunoreactivity to chromogranin A and synaptophysin, but the immunohistochemical profile was inconsistent with medullary thyroid carcinoma in that the tumor was negative for calcitonin, carcinoembryonic antigen (CEA), and thyroid transcription factor-1 (TTF-1)." (PMID 22369355, 2012).
heart failure (9 papers, 2012 to 2024). Inability of the heart to pump blood at an adequate rate to meet tissue metabolic requirements. "We examined whether chromogranin A (CgA) measurement in plasma may be valuable in assessing risk of death in elderly patients with symptoms of heart failure in a primary care setting." (PMID 24532383, 2014). "In particular, chromogranin A is an independent predictor of long-term mortality and heart failure-related hospitalization in patients with acute coronary syndromes." (PMID 36498765, 2022). "Before SN was identified as a potential biomarker of heart failure, acute coronary syndrome, and arrhythmogenesis, the prognostic values of chromogranin A and B were studied in similar conditions with variable results." (PMID 36498765, 2022). "CHGA has been suggested to be a fundamental regulator of blood pressure and endothelial barrier function and interestingly, an independent predictor of long-term mortality and heart failure of acute coronary syndromes." (PMID 22509262, 2012). "As cardiac production of chromogranin A and B, two related proteins, is increased in heart failure (HF), we hypothesized that SgII could play a role in cardiovascular pathophysiology." (PMID 22655045, 2012).
carcinoid syndrome (8 papers, 2015 to 2022). "Also, initial 24-hour urine 5-HIAA and Chromogranin-A were within normal limit ruling out carcinoid syndrome as a cause of the seizures." (PMID 26491586, 2015). "The diagnosis of carcinoid syndrome is based on elevated serum chromogranin A level and 24-hour urinary excretion of 5-hydroxyindoleacetic acid." (PMID 35713456, 2022). "Serum chromogranin A is the most common biomarker for assessing the extent of disease and monitoring treatment; carcinoid syndrome occurs in 19% of NETs and is characterized by chronic diarrhea or flushing." (PMID 35713456, 2022). "The diagnosis of carcinoid syndrome is based on the clinical presentation and supported by the presence of elevated levels of serum chromogranin A and 24-hour urinary 5-HIAA, a breakdown product of serotonin." (PMID 25323816, 2016). "To date, there have been 24 cases of NET brain metastases in the literature, with 3 patients presenting with carcinoid syndrome, 1 with increasing chromogranin A levels, and 1 diagnosed by radiologic imaging." (PMID 25810937, 2015). "Serum levels of 5-HIAA or chromogranin A may be used however, this appears to be of most benefit in patients presenting initially with carcinoid syndrome." (PMID 25763289, 2015). "In addition to the characteristic signs and symptoms, other objective findings that support concurrent carcinoid syndrome include elevations in chromogranin A, neuron-specific enolase, and serotonin in the blood and elevation in the 24-hour urinary collection of 5-hydroxyindolacetic acid (5-HIAA)." (PMID 27895950, 2016).
colon cancer (8 papers, 2011 to 2023). "In order to investigate these early diagnostic biomarkers for colon cancer, human chromogranin-A (CHGA) was further analyzed among the most powerful diagnostic biomarkers." (PMID 31207989, 2019). "In this study, we used a logistic regression-based meta-analysis to clarify associations of CHGA expression with colon cancer diagnosis." (PMID 31207989, 2019). "The decline of CHGA expression in the early stages of colon cancer is probably a new diagnostic biomarker for colon cancer diagnosis with high predicting possibility and verification performance." (PMID 31207989, 2019). "The results of this study suggest that a loss of CHGA expression from the normal colon and adjacent mucosa to colon cancer may be used as a valuable biomarker for early diagnosis of colon cancer patients." (PMID 35681650, 2022). "More importantly, CHGA may be a potential diagnostic biomarker for colon cancer patients." (PMID 35681650, 2022). "Previous studies showed that the CHGA protein produced mainly by the endocrine and neuroendocrine cells plays a role in cancer regulation, particularly as a novel biomarker for colon cancer patients." (PMID 37246623, 2023). "We have identified the diagnosis value of CHGA as a biomarker in colon cancer using meta-analysis based on gene expression data from RNA-seq and microarray, and most of these sequencing data were from colon cancer tissues." (PMID 35681650, 2022). "We showed that the candidate biomarkers were associated with the diagnosis, therapy, or prognosis of human cancers, including colon cancer, in which provided further evidence for the CHGA as a potential hub biomarker for the colon cancer." (PMID 31207989, 2019). "The results showed decreased expression of CHGA in the early stages of colon cancer as compared to the normal controls." (PMID 31207989, 2019). "The expression of the CHGA levels was markedly reduced in the colon cancer patients as compared with the CHGA expression in the normal controls in both microarray and RNA-seq data." (PMID 31207989, 2019). "Several other biomarkers from the PPI network, and similar genes to CHGA, were further predicted for future early diagnosis of colon cancer." (PMID 31207989, 2019). "Diagnostic receiver operating characteristic (ROC) test, immunohistochemistry (IHC), and biological network and function analysis were conducted to make the verification and confirmed that CHGA could be a future biomarker for colon cancer diagnosis." (PMID 35681650, 2022). "In order to further confirm our results from big data analyses, in the present study, we performed an IHC on our CRC TMA samples to verify the diagnosis value for CHGA in colon cancers, which proved that CHGA could be a promising biomarker for CRC diagnosis." (PMID 35681650, 2022). "CHGA might be considered as a novel, promising, and powerful biomarker for early diagnosis of colon cancer." (PMID 31207989, 2019). "This evidence indicated that CHGA might play an essential role in the initiation of colon cancer, from the normal colon tissue to early cancer." (PMID 31207989, 2019). "The down-expression of CHGA might be one of the critical mechanisms leading to colon cancer formation." (PMID 31207989, 2019). "In this study, CHGA expression was found to be decreased in the early stages of colon cancer in patients, as compared to CHGA expression levels in both the healthy populations and the normal colon cancer mucosa from the colon cancer patients." (PMID 31207989, 2019). "Furthermore, immunohistochemistry examination on our colon cancer tissue microarray samples further confirmed our bioinformatical prediction, indicating that CHGA may be used as a potential biomarker for early diagnosis of colon cancer patients." (PMID 35681650, 2022).
colon cancer (continued). "CHGA could be a potential candidate biomarker for diagnosing earlier colon cancer in the patients." (PMID 35681650, 2022). "CHGA might be a further biomarker for early colon cancer patients." (PMID 31207989, 2019). "Treatment of colon tumors with anti-DLL4 up-regulates markers of more differentiated colon cells (for example, ATOH1 and Chromogranin A) indicating that DLL4-Notch inhibition limits the stem/progenitor-like properties of colon tumor cells and promotes a more differentiated phenotype." (PMID 21831306, 2011). "However, there is no study concerning CHGA expression and early diagnosis in colon cancer." (PMID 31207989, 2019).
insulinoma (8 papers, 2014 to 2025). "ASCL-1 also regulates the expression of NE markers such as NCAM1, insulinoma-synaptophysin (SYP), insulinoma associated protein 1 (INSM1), chromogranin A (CHGA), and CGRP." (PMID 39858036, 2025). "The diagnosis of LCNEC requires positive immunohistochemical staining with chromogranin A, synaptophysin, and CD56, along with a morphological diagnosis, and insulinoma-associated protein 1 (INSM1) has been proposed as an additional marker but is still not an ideal or better marker." (PMID 38067335, 2023). "The LC/MS data obtained from the two glucagonoma cases (Case 1 pre‐ and post‐treatment, and Case 2), an insulinoma (Case 3) and 62 control samples from healthy individuals were interrogated for glucagon, CHGA, CHGB, SCG2, insulin, c‐peptide, and the internal standard bovine insulin." (PMID 29857350, 2018). "Chondroitin/dermatan sulfate conjugates from the rat insulinoma cell line, INS-1832/13, known to produce primarily the PG chromogranin-A, were enriched by anion-exchange chromatography after pronase digestion." (PMID 33757834, 2021). "The process of tumour detection involved biochemical screening tests including gastrin, glucose, insulin, chromogranin-A, pancreatic polypeptide, glucagon, vasointestinal polypeptide, prolactin and IGF-1 to assess for gastrinoma, insulinoma, enteropancreatic and anterior pituitary tumours." (PMID 31797261, 2020). "Similar phenomenon was seen in our previous study showing the strong expression of chromogranin A in insulinoma cells while serum levels of chromogranin A in patients were not elevated." (PMID 32124259, 2020).
lymph node metastasis (8 papers, 2014 to 2026). "Ultimately, this study suggested the molecular mechanism by which CHGA and UCHL1 mediate the invasive pathway in CRC cells associated with the pathological Stage III lymph node metastasis." (PMID 37246623, 2023). "Through bioinformatic analysis, we found that chromogranin A (CgA) was positively correlated with invasion and lymph node metastasis." (PMID 36899368, 2023). "We found highlight chromogranin A and UCHL1 are linked together, whose levels are influenced as a prognostic and predictive biomarker in CRC tumour tissues with lymph node metastasis (LNM) Stage III." (PMID 37246623, 2023). "We investigated CHGA and UCHL1 proteins correlate with lymph node metastasis (J Cell Mol Med." (PMID 41938501, 2026). "In univariate analysis, Chromogranin A expression in primary tumors or lymph node metastases did not significantly predict biochemical recurrence-free, cancer-specific, or overall survival." (PMID 28788048, 2017).
pancreatic tumor (8 papers, 2015 to 2025). "Gene expression profiling from independent Gene Expression Omnibus (GEO) datasets confirms that REST mRNA levels are elevated in human pancreatic tumor samples and correspond with lower levels of REST target genes such as SNAP25, CHGA, and PDGB5." (PMID 32080178, 2020). "For both biopsy and resected specimens in the liver, the tumor cells were positive for chromogranin A, but pancreatic tumor cells were negative for chromogranin A. There were discrepant results of chromogranin A between resected specimens in the pancreas and liver." (PMID 29938394, 2018).
lung carcinoma (7 papers, 2018 to 2025). "On the basis of the Japan Lung Cancer Society Guidelines, pathological diagnosis using NE markers such as chromogranin A, synaptophysin, and NCAM/CD56 are currently used to distinguish SCLC from other lung NE tumors in Japan." (PMID 41220940, 2025). "In contrast, most tuft cell-like lung cancers were negative for the highly specific neuroendocrine markers, chromogranin A and synaptophysin, and TTF1, a marker of pulmonary adenocarcinoma and SCLC." (PMID 36402755, 2022). "The regulatory potential of NE-DMRs was further validated in vitro using paired ATAC- and RNA-seq and revealed both proximal and distal regulatory elements of canonical NE-marker genes such as CHGA, NCAM1, INSM1, as well as a number of novel candidate markers of NE lung cancer." (PMID 32707835, 2020). "In order to directly identify candidate mediators that are relevant to both lung cancer tumorigenesis and patient survival, we began with genes displaying significant correlation with mRNA levels of LMO1 and neuroendocrine markers CHGA, SYP and ENO2 levels in the MDACC dataset." (PMID 30038707, 2018). "To further evaluate the association of LMO1 expression with neuroendocrine differentiation in lung cancer cells, we examined the correlation between LMO1 mRNA levels and mRNA levels of neuroendocrine markers, including chromogranin A (CHGA), synaptophysin (SYP) and neuron-specific enolase-2 (ENO2)." (PMID 30038707, 2018).